PRSS3 (serine protease 3)
Diseases named in the same sentence as PRSS3 in open-access papers (continued):
Sharing a sentence is not in itself a finding about the gene and the disease.
sarcoidosis (1 paper, 2022). Sarcoidosis is a multisystemic disorder of unknown cause characterized by the formation of immune granulomas in involved organs. "Of these genes, we found that patients who carried missense mutations of rs76740888 (Chr9:33796673 G to A) on the PRSS3 gene had a higher probability of a chronic sarcoidosis prognosis." (PMID 35860586, 2022). "Among the three immune-related genes with significant mutation frequencies, the PRSS3 and CNN2 genes were detected, which contained the highest missense mutation ratios, at 100% and 97%, respectively, among the 116 sarcoidosis patients." (PMID 35860586, 2022). "Our study provides new insights into the molecular pathogenesis of sarcoidosis and identifies novel genetic alterations in this disease, especially PRSS3, which may be promising targets for future therapeutic strategies for chronic sarcoidosis." (PMID 35860586, 2022).
squamous cell carcinoma of the head and neck (1 paper, 2022). "For example, although HPV infection is a well-known pathogen for squamous cell carcinoma of the head and neck, its infection may induce a decreased PRSS3 level in this cancer type." (PMID 36618965, 2022).
triple-negative breast carcinoma (1 paper, 2017). An invasive breast carcinoma which is negative for expression of estrogen receptor (ER), progesterone receptor (PR), and human epidermal growth factor receptor 2 (HER2). "Among the 286 IDC patients, we got 26 cases of triple-negative breast cancer (TNBC) patients; we correlated PRSS3 protein expression with TNBC patents’ clinical characteristics." (PMID 28423522, 2017).
tumor (32 papers, 2008 to 2025). "PRSS3/mesotrypsin is an atypical isoform of trypsin, the upregulation of which has been implicated in promoting tumor progression." (PMID 28463992, 2017). "We had shown by in situ hybridization that the in vivo expression of PRSS3 transcript is associated with the tumor vasculature." (PMID 26318044, 2015). "Mesotrypsinogen (PRSS3) has been found to be overexpressed in pancreatic cancer cell lines and promotes cell proliferation and invasion in cell culture, while in vivo it causes both tumor growth and metastasis." (PMID 24474939, 2013). "In addition, the researchers also found that PRSS3 is also expressed in the ovarian stroma, suggesting that the expression of PRSS3 might also be associated with the tumor's microenvironment." (PMID 28423522, 2017). "The IHC results demonstrated that CAF signature genes COL1A2, MFSD5, NOTCH3, and PRSS3 were highly expressed in tumor tissues." (PMID 40781483, 2025). "There is an ongoing debate over PRSS3’s involvement in tumor growth; whereas some studies attribute a positive role, on the other hand, others claim that it has a tumor-suppressive role." (PMID 40909962, 2025). "KLK6, PRSS22, and PRSS3 are all secreted serine proteases, the first two identify CC tumor cells that are useful as tumor markers because they identify aggressive tumor cells." (PMID 40909962, 2025). "Fluorescent images of the whole lungs and quantified tumor area suggested that high expression of PRSS3 and FOSL1 resulted in larger primary lung tumors, but elevated PAR2 levels did not have similar effects." (PMID 37395651, 2023). "To further explore the contribution of PRSS3 transcripts to tumor heterogeneity, we used the TCGA dataset to analyze their clinical relevance." (PMID 35480112, 2022). "Here in the current study, we firstly reported an upregulated expression of PRSS3 and elucidated its prognostic value as well as tumor-promoting effects in DLBCL." (PMID 36618965, 2022). "Their data demonstrated a tumor-suppressing role of PRSS3 in HCC via multiple pathways, including downregulation of matrix metallopeptidase 2 (MMP2) and deactivating MEK1-ERK1/2 signaling." (PMID 36618965, 2022). "The pattern of mPRSS3Low versus umPRSS3High was further confirmed in tumor samples showing more similarity between PRSS3 and PRSS3-V2, whereas PRSS3-V1 was more phenotypically defined with mPRSS3Low and umPRSS3High groups." (PMID 35480112, 2022). "We hereby explored the contribution of PRSS3 transcripts to tumor functional heterogeneity by systematically dissecting the expression of four known splice variants of PRSS3 (PRSS3-SVs, V1~V4) and their functional relevance to HCC." (PMID 35480112, 2022). "Epigenetic silencing of RASSF1A, PRSS3, or any of the SFRP genes is significantly associated with advanced tumor stage (P < 0.001, P < 0.04, and P < 0.005, respectively)." (PMID 28587272, 2017). "Our microarray analyses have suggested that PRSS3 is expressed by EC and from cancer specimens (tumor-EC)." (PMID 26318044, 2015). "Recent studies evaluating the consequences of PRSS3 over-expression or silencing in tumor cells indicated that its activity favors tumor progression." (PMID 26318044, 2015). "There are conflicting reports in the literature of the role of trypsin or PRSS3 in tumor progression, with some studies assigning a positive role, while others have reported that trypsin or PRSS3 plays a tumor suppressive role." (PMID 21203532, 2010). "In order to investigate the in vivo localization of ADAM23, GPNMB and PRSS3, human tumor tissues were analyzed by in situ hybridization." (PMID 18447899, 2008). "Under both conditions the expression of ADAM23, FAP, GPNMB and PRSS3 genes was much higher in EC isolated from tumor specimens, as shown by the fold difference values." (PMID 18447899, 2008).
tumor (continued). "Through comparative analysis of the expression levels of PRSS3 transcripts, including PRSS3 and its four SVs, in 50 paired tissue samples, we found that PRSS3-V2 and -V1 were predominantly present in both normal and tumor tissues." (PMID 35480112, 2022). "Their findings indicated that PRSS3 may participate in tumor metastasis and their further data confirmed a significant correlation between PRSS3 expression and metastasis in clinical samples." (PMID 36618965, 2022). "Through meta-analysis of published datasets, we identified tumor expression of PRSS3 and KLK5 transcripts as prognostic of poor survival and cancer progression in LAC but not SCC, which indicates that the pathways studied may be specific to LAC." (PMID 30755669, 2019). "It seems very plausible that PRSS3 produced by TdEC may contribute to tumor angiogenesis, invasion and metastasis through its peptidase activity." (PMID 18447899, 2008). "Here we describe for the first time a much higher expression of ADAM23, FAP, GNPNB and PRSS3 in EC derived from six tumor samples than in EC from four normal tissue specimens examined by real-time PCR, whose origin differed from that investigated by microarray analysis." (PMID 18447899, 2008). "On one hand, PRSS3 is decreased in certain cancer types and may play tumor-suppressing roles." (PMID 36618965, 2022). "Moreover, they showed the tumor-promoting role of PRSS3 depended on its enzymatic activities." (PMID 36618965, 2022). "The qPCR analysis quantitatively confirmed the upregulation of MFSD5, PARVA, PRSS3, OLFML2A, and NOTCH3 at the mRNA level in tumor tissues, with statistically significant differences compared to adjacent tissues." (PMID 40781483, 2025). "Immunohistochemical analysis with anti-PRSS3, anti-PRSS22, and anti-CEA antibodies applied to H&E(+) LNs demonstrated that a fraction of the tumor cells in the LNs, displayed positive staining for both PRSS3 and PRSS22." (PMID 40909962, 2025). "For this study of a CCA tumor PDX with the highest expression levels of our drug targets, we observed high levels of trypsin 3 (PRSS3) in the PAX165 tumor." (PMID 38473407, 2024). "Notably, our findings revealed that C2 UBE2C+ tumour cells had stronger efferent signals in the PARs signalling pathway, and actively interacted with pericytes, fibroblasts and endothelial cells, and high expression levels of the involved signalling gene PRSS3." (PMID 38894657, 2024). "Enriched PRSS3, PAR2, and FOSL1 in human tumor samples and their correlations with worse outcomes reveal their clinical significance." (PMID 37395651, 2023). "Therefore, targeting PRSS3 may represent a potential intervention strategy in tumor treatment." (PMID 36618965, 2022). "The up-regulated in IPF is PRSS3, a well-known oncogene that promote cell migration and cancer metastasis, while the down-regulated in IPF is MIR126, which functions as a tumor suppressor that inhibit cell migration." (PMID 32244228, 2020). "In the next phase of the study, we intend to further validate the expression of PRSS3 using a cell model and a nude mouse model, which can aid in exploring its molecular mechanism of action in regulating the growth of IDC tumor cells." (PMID 28423522, 2017). "For example, the serine proteases PRSS3 (also known as trypsinogen IV), PRSS8 (prostasin), and PRSS21 (testisin) were categorized as tumor-protective proteases in the human degradome." (PMID 22761798, 2012). "PRSS3 and PRSS22 protein expression in CC primary tumors and normal colon tissue was studied by the consecutive staining immunohistochemistry technique using anti-CEA mAb to identify tumor cells." (PMID 40909962, 2025).
tumor (continued). "Of these mRNAs, the ADAM23, FAP, GPMNB and PRSS3 were found in the tumour-derived endothelium, but no expression was observed in tumour cells." (PMID 30189837, 2018). "Restriction enzyme digestion analyses indicated that PRSS3 is expressed by tumor-EC while PRSS1 and PRSS2 are not." (PMID 26318044, 2015). "The druggability of PDPN, PRSS3, GREM1, and LGALS1, alongside the established relevance of FAP, provides multiple entry points for stromal-directed interventions that could complement tumor cell–targeted therapies." (PMID 41198614, 2025).
cancer (22 papers, 2008 to 2025). A tumor composed of atypical neoplastic, often pleomorphic cells that invade other tissues. "In the second family in which MPT21 and two relatives were tested, we found four LP variants (BPIF1, BCORL1, ROPN1, and PRSS3) and four other cancer-related genes (TUBB2B, CFAP54, PSG2, and SIRPB1)." (PMID 39408606, 2024). "Finding the substrates of PRSS3 is important for determining the underlying mechanisms through which PRSS3 promotes invasion and cancer metastasis." (PMID 37395651, 2023). "Noteworthy among these proteases is mesotrypsin (also known as PRSS3), a serine endopeptidase belonging to the chymotrypsin superfamily and associated with increased malignancy in several cancers, including lung, pancreas, breast, and prostate cancers." (PMID 37609678, 2023). "On the one hand, PRSS3 was shown to be upregulated in association with cancer metastasis, recurrence and poor prognosis." (PMID 35480112, 2022). "PRSS3 has long been implicated in the pathogenesis of several malignancies and is therefore a promising biomarker and potential therapeutic target for cancer." (PMID 35480112, 2022). "PRSS3 has been found to be implicated in the progression and metastasis of several cancer types." (PMID 40565234, 2025). "For instance, the pattern of PRSS3 downregulation associated with the clinical relevance of HCC patients was similar to that of TMEM45A and VNN1, which are positively co-expressed genes of PRSS3 in HCC patients showing oncogenic effects on cancer-associated events." (PMID 35480112, 2022). "Therefore, customized generation of more isoform-specific antibodies will be the subject of our future investigation to explore the molecular mechanisms underlying the dual role of PRSS3 transcript isoforms in cancer development." (PMID 35480112, 2022). "However, the functional roles associated with the expression of PRSS3 in cancer development are debatable." (PMID 35480112, 2022). "An association between serine protease 3 (PRSS3) expression and a worseprognosis in cancer patients have been recently shown by microarray data,but its role in the patho-physiology of tumors is mostly unknown." (PMID 26318044, 2015). "Most of these proteins are recognized as potential prognostic biomarkers in liver (TFRC and GPLD1), renal (IGHG1, PRCP, SAA1/2, and IL1RAP) and digestive (PRSS3) cancers in the Human Protein Atlas database." (PMID 41155404, 2025). "In this research, PRSS3 was detected as differentially expressed for the first time in cancer plasma, but additional research is warranted to explore the potential of PRSS3 in non-invasive cancer diagnostics." (PMID 40565234, 2025). "Kaplan–Meier (K-M) analysis revealed that PRSS3-V2Low was a favorable factor for the overall survival of HCC patients based on cancer stage and grade, in which PRSS3-V2Low patient groups with low-grade tumors showed significantly favorable outcomes (P=0.011)." (PMID 35480112, 2022). "Consistent with this, epigenetic silencing of PRSS3 was found in several cancer types, and our previous study showed intragenic DNA methylation within the extended promoter region contributing to PRSS3/TRY-4 downregulation in HCC." (PMID 35480112, 2022). "Having found that KLK5 knockdown phenocopied the effects of PRSS3 knockdown on cancer cell invasion and proliferation, we next evaluated the potential association of KLK5 gene expression in LAC with survival and progression." (PMID 30755669, 2019). "When overexpressed in a SCC cell line, a PRSS3-derived fusion protein led to increased migration of the cancer cells through an endothelial cell layer, suggesting a potential role for PRSS3/mesotrypsin in metastatic dissemination." (PMID 30755669, 2019). "In vivo investigation by in situ hybridization established that ADAM23, GPNMB and PRSS3 expression is localized on blood vessels of human cancer specimens." (PMID 18447899, 2008).
cancer (continued). "Variants in four genes (ROPN1, PRSS3, BPIFB1, and BCORL1) were detected in all individuals from Family 2, while four (TUBB2B, CAFAP54, PSG2, and SIRPB1) were exclusive of the MPT21 index case and her relative with cancer (MPT21.2)." (PMID 39408606, 2024). "In this regard, delineation of the heterogeneity of PRSS3 expression and epigenetic regulation is critical for clarifying the molecular basis of PRSS3 transcripts, thus facilitating functional interpretation of the paradoxical effects of PRSS3 in cancer development." (PMID 35480112, 2022). "Accordingly, we found divergent expression of PRSS3-SVs toward bipolarity following clinical progression from downregulation in early HCC to upregulation in advanced cancer, unveiling the molecular basis of PRSS3 in tissue-selective expression of its splice transcripts in HCC." (PMID 35480112, 2022). "The expression and function of PRSS3 in different cancers are completely different." (PMID 36618965, 2022). "Notably, the expression of PRSS3-SVs was dynamically altered following clinical progression from downregulation in early HCC to upregulation in advanced cancer." (PMID 35480112, 2022). "Using an LAC-derived cell line with high endogenous expression of PRSS3, we show that silencing of PRSS3 gene expression, or inhibition of mesotrypsin activity, suppresses cancer cell growth and invasion, implicating mesotrypsin as a driver of malignancy in LAC." (PMID 30755669, 2019). "Moreover, ADAM23, GPMNB and PRSS3 expression only occurred in the blood vessels of human cancer samples." (PMID 30189837, 2018). "Methylated PRSS3 might be a suitable gene for the detection of malignancies, although more studies are needed to elucidate the specificity of this gene for the detection of serum PRSS3 in cancer patients." (PMID 28423522, 2017). "On the other hand, PRSS3 may exert oncogenic functions in more cancer types." (PMID 36618965, 2022). "Collectively, we can conclude that PRSS3, PAR2, and FOSL1 play important roles in the invasiveness and metastasis of cancer cells and that SS strengthens the metastatic ability of circulating cancer cells by upregulating these three genes." (PMID 37395651, 2023). "To further confirm the importance of PRSS3, PAR2, and FOSL1 in promoting invasion and cancer metastasis, we overexpressed these three genes in A549‐C3 cells, which are the parental cells of A‐SSP6 cells and had low levels of PRSS3, PAR2, and FOSL1." (PMID 37395651, 2023). "Next, to examine the impacts of knocking down PRSS3, PAR2, and FOSL1 on the in vivo metastatic potential of A‐SSP6 cells, we first injected cancer cells into the tail vein of NOD/SCID mice and observed the colonies formed in the left lungs." (PMID 37395651, 2023). "Among the genes that were particularly upregulated by SS, PRSS3, PAR2, and FOSL1 played important roles in cell invasion and cancer metastasis." (PMID 37395651, 2023). "Together, these results explain the potential mechanisms by which PRSS3 and PAR2 facilitate the invasiveness and metastatic ability of cancer cells." (PMID 37395651, 2023). "To elucidate the mechanisms through which SS upregulates PRSS3, PAR2, and FOSL1 to promote cell invasion and cancer metastasis, we first examined the kinases that were reported to modulate the activity and expression of AP‐1." (PMID 37395651, 2023). "The RNA-seq data from the Cancer Model Repository (LIMORE) and the DepMap portal revealed that PRSS3 as a whole was differentially expressed in HCC cell lines." (PMID 35480112, 2022). "Serine protease 3 (PRSS3) is one of the isoforms of trypsinogen, which plays an important role in the development and progression of many types of malignant tumors." (PMID 28423522, 2017). "A similar trypsinogen secreted from cancer cell lines, degrades subendothelial cell extracellular matrix (ECM) and it has been shown that enzymes similar to PRSS3 degrade fibronectin and aggrecan." (PMID 23437119, 2013).
cancer (continued). "We also used a lung orthotopic model that was established in our previous study to investigate the importance of PRSS3, PAR2, and FOSL1 in the spontaneous metastasis of cancer cells by injecting A‐SSP6 cells transfected with shRNAs into the right lungs of NOD/SCID mice." (PMID 37395651, 2023). "Several inhibitors with the Kunitz domain have been identified as substrates of PRSS3, but none has been reported in cancer." (PMID 37395651, 2023). "While SVs have emerged as new candidates for diagnostic and prognostic biomarkers and therapeutic targets, the expression and function of PRSS3-SVs in cancer development have never been systematically addressed." (PMID 35480112, 2022). "In the present study, we identify PRSS3 gene expression as a prognosticator of poor survival and cancer progression specifically in LAC but not in SCC." (PMID 30755669, 2019). "PRSS3 is expressed in the acinar cells of the pancreas but not in the normal ductal epithelium, and PRSS3 expression was significantly enhanced in cancer tissues with vascular and lymphatic metastasis." (PMID 28423522, 2017). "As a result, seven DEGs correlated with more than 10 TR-DDR genes (r>0.3) in at least 10 cancers were regarded as candidate genes, including COL2A1 (the R ranged from 0.39 to 0.60), MAGEA4 (0.24–0.62), FCRL4 (0.33–0.62), ZIC1 (0.24–0.33), LCN15 (0.20–0.41), PRSS3 (0.24–0.35), CSAG1 (0.31–0.38)." (PMID 36081518, 2022). "We also obtained another attractive gene, serine protease 3 (PRSS3), which has not been well studied in cancer but was highly upregulated by SS." (PMID 37395651, 2023).
infection (3 papers, 2019 to 2022). The state of being infected such as from the introduction of a foreign agent such as serum, vaccine, antigenic substance or organism. "Therefore, retention of the PRSS3 trypsinogen in the human neuronal cells might be one of the pathological mechanisms in EV-A71 infection." (PMID 35896602, 2022). "In our preliminary data, it was found that EV-A71 infection did not affect the expression level of PRSS3 mRNA at 12- and 24 h post-infection (data not shown)." (PMID 35896602, 2022).